MITD1 (microtubule interacting and trafficking domain containing 1)
Description:
Required for efficient abscission at the end of cytokinesis, together with components of the ESCRT-III complex.
Synonyms: LOC129531
Tractability: Small molecule: a structure with a bound ligand is known. Antibody: UniProt places it where antibodies can reach, with medium confidence. PROTAC: ubiquitination databases record sites on it; its protein half-life has been measured.
Gene: Protein-coding gene on chromosome 2 (99,161,427 to 99,181,058, reverse strand). Ensembl gene ENSG00000158411.
Subcellular location: Late endosome membrane; Midbody; Membrane
Subcellular location (Human Protein Atlas): Vesicles
Gene Ontology:
Molecular function: identical protein binding; phosphatidylinositol binding; protein binding; protein domain specific binding
Biological process: midbody abscission; mitotic cytokinesis; multivesicular body sorting pathway; negative regulation of protein binding; viral budding via host ESCRT complex
Cellular component: extracellular exosome; membrane; midbody; late endosome membrane
Genetic constraint (gnomAD): Loss-of-function variants: 8 observed, 13.03 expected, observed/expected ratio (o/e) 0.61, 90% interval 0.36 to 1.11. The upper end of that interval is the gene's LOEUF score, 1.11, which puts it in group 4 of 6, group 1 being the genes least tolerant of losing a copy. Missense variants: 137 observed, 158.92 expected, observed/expected ratio (o/e) 0.86, 90% interval 0.75 to 0.99. Synonymous variants: 57 observed, 63.29 expected, observed/expected ratio (o/e) 0.9, 90% interval 0.73 to 1.12.
Homologues: Orthologues: chimpanzee MITD1 (99% identical), macaque MITD1 (97% identical), rabbit MITD1 (88% identical), pig MITD1 (87% identical), rat Mitd1 (86% identical), mouse Mitd1 (85% identical), dog MITD1 (84% identical), guinea pig MITD1 (84% identical), tropical clawed frog mitd1 (69% identical), zebrafish mitd1 (64% identical), Caenorhabditis elegans Y66D12A.10 (33% identical), Drosophila melanogaster CG14985 (33% identical), and 1 more.
Diseases named in the same sentence as MITD1 in open-access papers:
MITD1 is named in the same sentence as 20 diseases in open-access papers, as found by Europe PMC text mining. Sharing a sentence is not in itself a finding about the gene and the disease. The quoted sentences say what the papers report.
liver cancer (3 papers, 2022). An epithelial or non-epithelial malignant neoplasm that arises from the liver. "Previous studies revealed that MITD1 was abnormally expressed in patients with liver cancer and bladder cancer and had a significant correlation with prognosis." (PMID 36046690, 2022). "For patients with liver cancer, higher MITD1 expression was correlated with poor OS, PFS, RFS, and disease-free survival (DSS)." (PMID 36291174, 2022). "For instance, MITD1 has been reported as a novel liver cancer biomarker involved in cytokinesis." (PMID 36428813, 2022).
Clear Cell Renal Cell Carcinoma (2 papers, 2022 to 2023). "Moreover, MITD1 deficiency has been discovered to hinder the growth and migration of clear cell renal cell carcinoma by inducing ferroptosis through the TAZ/SLC7A11 pathway." (PMID 38159255, 2023).
hepatocellular carcinoma (2 papers, 2022). A malignant tumor that arises from hepatocytes. "A study found that MITD1 was able to serve as a predictor for human hepatocellular carcinoma prognosis and correlated with immune infiltrating cells around the carcinoma." (PMID 36046690, 2022). "MIT-domain containing protein 1 (MITD1) has been reported to play an important role in hepatocellular carcinoma, while it remains unclear whether MITD1 is involved in ccRCC." (PMID 36046690, 2022).
bladder cancer (1 paper, 2022). "In another research, the researchers identified MITD1 as one of the most important survival-related genes in bladder cancer, which was able to influence the migration ability of tumor cells by knocking down or overexpressing it." (PMID 36046690, 2022).
breast carcinoma (1 paper, 2022). "For breast cancer, single-cell level analysis, immunochemistry, and in vitro experiments were performed to explore the mechanism of MITD1." (PMID 36291174, 2022). "In breast cancer, MITD1 inhibited cell proliferation and migration and serves as a new biomarker." (PMID 36291174, 2022).
gastric cancer (1 paper, 2022). A primary or metastatic malignant neoplasm involving the stomach. "Simultaneously, a low MITD1 expression level was also associated with poor OS, first progression (FP), and post-progression survival (PPS) in gastric cancer." (PMID 36291174, 2022).
lung carcinoma (1 paper, 2022). "Similarly, patients with lung cancer with high MITD1 expression had poorer OS and FP but a better PPS." (PMID 36291174, 2022).
ovarian carcinoma (1 paper, 2022). A malignant neoplasm originating from the surface ovarian epithelium. "In contrast, high MITD1 expression levels were associated with poor OS and PFS in ovarian cancer." (PMID 36291174, 2022).
tumor (3 papers, 2022 to 2023). "Then, we further analyzed publicly available data of ccRCC from TCGA and found that the expression of MITD1 was significantly higher in tumor cases compared with normal cases in paired or unpaired ccRCC tissues." (PMID 36046690, 2022). "Subsequent overexpression experiments demonstrated that MITD1 knockdown induced ferroptosis and suppressed tumor growth and migration through the TAZ/SLC7A11 pathway." (PMID 36046690, 2022). "In our study, we analyzed public databases and found that MITD1 was highly expressed in ccRCC and the expression level was related to tumor stage and clinical T stage." (PMID 36046690, 2022). "Therefore, MITD1 is expected to be a prognostic biomarker of ccRCC and a new therapeutic target for tumor ferroptosis." (PMID 36046690, 2022). "MITD1 may regulate cancer development by altering the tumor microenvironment, and MITD1 expression may predict the response to immune checkpoint blockade, platinum, and poly ADP-ribose polymerase inhibitor therapies." (PMID 36291174, 2022). "Moreover, we investigated MITD1 protein levels using the Clinical Proteomic Tumor Analysis Consortium (CPTAC) dataset." (PMID 36291174, 2022). "In addition, MITD1 regulated proliferation and invasion of tumor cells and was able to alter the tumor microenvironment by recruiting and regulating immune infiltrating cells." (PMID 36046690, 2022). "Out of the identified regulators, six genes (SLC6A3, MITD1, CCS, LIPT2, ATOX1, and GLS) showed increased expression in tumor tissues, while PDHB had higher expression in normal tissues." (PMID 38159255, 2023). "Specifically, the expression levels of SLC6A3, MITD1, and PDHA1 exhibited an increasing trend with tumor pathological stage, whereas CCS, LIPT2, PDHB, and PDHA1 displayed a decreasing trend in response to radiation therapy." (PMID 38159255, 2023). "The results show a significant increase in the expression of SLC3A3, MITD1, LIPT2, ATOX1, PDHB, and GLS in tumor tissues compared to normal esophageal tissues." (PMID 38159255, 2023). "Thus, we performed a pan-cancer expression analysis of MITD1 in 33 cancer types using The Cancer Genome Atlas (TCGA), Tumor Immune Estimation Resource (TIMER), and Human Protein Atlas (HPA), including data on MITD1 expression, clinical survival prognosis, TME, TMB, MSI, HRD, and ploidy." (PMID 36291174, 2022).
cancer (2 papers, 2022). A tumor composed of atypical neoplastic, often pleomorphic cells that invade other tissues. "MITD1 expression was associated with immune cells in 31 cancer types." (PMID 36291174, 2022). "In some cancers, high MITD1 expression was associated with a more favorable prognosis." (PMID 36291174, 2022). "The present study investigated MITD1 expression in different cell types, normal tissues, and cancer tissues." (PMID 36291174, 2022). "Based on available data in The Cancer Genome Atlas, we found the expression of MITD1 increased through bioinformatics analysis and high MITD1 expression suggests a poor prognosis." (PMID 36046690, 2022). "In our study, we found that MITD1 expression was related to infiltrating immune cells in 31 cancer types." (PMID 36291174, 2022). "This study explored the expression, prognostic value, and immune infiltration profile of MITD1 in different cancers using several databases." (PMID 36291174, 2022). "Nonetheless, a few studies have revealed that MITD1 plays multiple roles in the progression of various cancers." (PMID 36291174, 2022). "To assess the role of MITD1 in malignant tumors, we first investigated the expression of MITD1 in various malignant tumors in the GEPIA." (PMID 36046690, 2022). "For ESTIMATE scores, eight and nine cancers were positively and negatively correlated with MITD1 expression, respectively." (PMID 36291174, 2022). "Our first pan-cancer study of MITD1 has shown that it plays different roles in cancer development and therapy." (PMID 36291174, 2022). "Additionally, the role of MITD1 in other types of cancer and the functional mechanism in BRCA warrant further investigation." (PMID 36291174, 2022). "In 15 cancers, MITD1 expression was higher than that in the corresponding control tissues." (PMID 36291174, 2022). "This first pan-cancer study of MITD1 showed that MITD1 expression varies in different cancers." (PMID 36291174, 2022). "In addition, we used TCGA and GEO datasets to analyze the relationship between MITD1 and the prognosis of patients with different cancers." (PMID 36291174, 2022). "However, MITD1 was expressed at lower levels in the other 12 cancers than in control tissues." (PMID 36291174, 2022). "In addition, Transwell and wound healing assays revealed that MITD1 could inhibit cancer cell migration." (PMID 36291174, 2022). "Therefore, we explored the pan-cancer role of MITD1 using multiple databases." (PMID 36291174, 2022). "Therefore, MITD1 may predict the response to platinum and PARPi in different cancers." (PMID 36291174, 2022).
MITD1 also shares sentences with these, for which no sentence is quoted: esophageal carcinoma (1 paper); kidney chromophobe (1); lung adenocarcinoma (1); lung squamous cell carcinoma (1); ovarian serous cystadenocarcinoma (1); prostate adenocarcinoma (1); skin cutaneous melanoma (1); thyroid carcinoma (1); uterine carcinosarcoma (1); uterine corpus endometrial carcinoma (1).